CD38 (CD38 molecule)
Diseases named in the same sentence as CD38 in open-access papers (continued):
Sharing a sentence is not in itself a finding about the gene and the disease.
Sepsis (continued). "Chaturvedi and colleagues found that more than 7% of CD38+HLA-DR+ cells within the CD8+ T cell pool distinguished patients with HLH from those with sepsis." (PMID 37751296, 2023). "CD38 was also unchanged, which is common for patients, as the early phase of sepsis has minimal activation of circulating CD8+ T cells or an increased expression level of CD38." (PMID 37175761, 2023). "The activation of ERK1/2 and NF-kB p65 results in exacerbation of pulmonary injury and inflammatory response in CD38 −/− sepsis mice." (PMID 36077708, 2022). "Upregulation of CD38 in septic patients has been reported previously, however detailed understanding on the role and regulation of CD38 in sepsis and monocyte exhaustion is still missing." (PMID 34777396, 2021). "In the previous results, we found that CD38 deletion can lead to more severe sepsis related-liver injury, and there are studies reporting that in sepsis-related liver injury, pyroptosis activates immune cells and hugely induces inflammation." (PMID 33860064, 2021). "In a separate model of sepsis, induced by cecal ligation in rats, CD38 expression and cADPR production increased in the central nervous system." (PMID 31963337, 2020). "We found that HSPCs (CD34+ cells and CD34+CD38+ cells) were migrated to the peripheral blood during sepsis, which is consistent with previous studies." (PMID 33542693, 2020). "CD38 is one of the well-known regulators of innate immunity, whose dysregulation contributes to sepsis." (PMID 30915370, 2019). "Many studies have proven that an attenuated Gram-positive bacterium induces sepsis in a CD38-blocking model." (PMID 30915370, 2019). "To investigate the potential roles of CD38 in LPS-challenged sepsis, we observed the phenotype change in a CD38−/− mouse model." (PMID 30915370, 2019). "Since dysregulated innate immune response largely contributes to sepsis, we turned our attention to CD38, an important regulator of innate immunity." (PMID 30915370, 2019). "The frequency of circulating CD34+CD38− HSCs was significantly decreased on the days 1 and 7 of sepsis compared to the healthy controls." (PMID 30824730, 2019). "Sepsis increased the percentages of both CD34+ CD38− and CD34+ CD38+ with phosphorylated STAT3 and this effect was diminished by DAPT treatment, suggesting partial crosstalk between these two pathways." (PMID 26272069, 2015). "This study aimed to elucidate the impact of CD38 ligation on sepsis using single-cell and single-nucleus RNA sequencing (scRNA-seq and snRNA-seq, respectively) to identify a novel therapeutic target for severe sepsis." (PMID 39568061, 2025). "Besides, histopathology of lung tissues of mice with sepsis revealed inhibition of CD38 at 3 h after modeling, which reduced CLP‐induced inflammatory cell infiltration, as well sepsis‐caused kidney injury was mitigated." (PMID 40145840, 2025). "However, the role of CD38 in either protecting against or exacerbating sepsis-induced inflammation remains controversial." (PMID 39568061, 2025). "Targeting CD38 therapy reduces inflammatory response in monocytes and in sepsis mice model." (PMID 40145840, 2025). "Additionally, the circulating levels of CD31, a well-known ligand of CD38, also increase in patients with sepsis." (PMID 39568061, 2025). "Mechanistically, CD38‐HIF‐1α/glycolysis/MGO loop exacerbates sepsis‐induced immune dysregulation." (PMID 40145840, 2025). "We investigated Cd38 expression in the various organs of sepsis-induced mice after LPS exposure." (PMID 39568061, 2025). "That study also suggested that inhibiting CD38 could be a therapeutic strategy to delay the onset and progression of sepsis-induced acute kidney injury." (PMID 41488275, 2025). "Moreover, the expression levels of CD38 were increased by lipopolysaccharide (LPS) stimulation of monocytes from sepsis patients compared to monocytes from healthy donors." (PMID 40145840, 2025).
Sepsis (continued). "A Cd38‐deficient mouse model lacking exons 2–4 of the Cd38 gene was generated using the CRISPR‐Cas9 approach to assess the impact of CD38 on sepsis." (PMID 40145840, 2025). "The qRT‐PCR results uncovered that the mRNA expression of CD38 in the Sepsis group was significantly higher than that of patients in the Surgery group, Mild group, and HC group, thus further confirming the specificity of CD38high C1 monocytes expression in patients with sepsis." (PMID 40145840, 2025). "To explore whether CD38 drove dysfunctional activation of inflammation in monocytes of sepsis, we detected an induction of CD38 expression in primary CD14+ monocytes upon LPS and IFN‐γ stimulation and performed bulk RNA‐sequencing." (PMID 40145840, 2025). "As the development of sepsis is mediated by complicated cell–cell interactions via cytokines between various cell types, the impact of CD38 ligation on sepsis needs to be investigated in vivo and in individual cells to clarify the alterations in cell–cell interactions." (PMID 39568061, 2025). "Thus, the effects of CD38 blockade in bacterial-sepsis-induced AKI in experimental models is contradictory." (PMID 36831262, 2023). "The surface biomarker CD38 was more likely to be expressed in common myeloid progenitors, whose expansion in peripheral blood may indicate severe sepsis." (PMID 36304125, 2022). "Therefore, we concluded that the CD38-regulated TLR4-NLRP3-GSDMD pathway plays an important role in liver injury of septicemia and its mechanism needs further study." (PMID 33860064, 2021). "Blocking the CD38 pathway protected the hippocampus from apoptosis, oxidative stress, and ultrastructural morphology damage in a septic rat, and also, the hearts, livers, and kidneys of septic rats were protected from sepsis-induced damage." (PMID 33860064, 2021). "Thus, clinically, IFN-γ or CD38 can be potential targets for drug development to attenuate sepsis-induced kidney injury." (PMID 30915370, 2019). "We had two hypotheses; one was that CD38 knockout would impair the stronger innate immune response in sepsis, thus resulting in an attenuated sepsis syndrome with a less severe kidney damage." (PMID 30915370, 2019). "These reminded us that maybe IFN-γ is the key molecule in the LPS-induced sepsis pathway in the CD38−/− mice." (PMID 30915370, 2019). "However, the flavonoids used as CD38 inhibitors in these studies also exert antioxidant and anti-inflammatory effects and may directly influence the pathology of sepsis." (PMID 39568061, 2025). "Similarly, in our study, NAD+ consumption induced mitochondrial insufficiency elicited the stabilization of HIF‐1α, which in turn triggered the metabolic shift to aerobic glycolysis, thus CD38‐NAD+‐HIF‐1α axis was found to induce metabolic rewiring of monocytes in sepsis." (PMID 40145840, 2025). "Therefore, further experimental studies are needed to confirm the role of CD38 in the immunosuppressive phase of sepsis and whether selective interference of CD38 activity can improve the immunopathological changes caused by excessive inflammation." (PMID 36998049, 2023). "In addition, CD38 deficiency could up-regulate ERK1/2 and NF-κB pathways in sepsis mice, accompanied by the expression of inflammatory cytokines IL-1β and chemokine MCP-1 in the lung tissues, resulting in increased pathological injury in septic lung tissues." (PMID 36998049, 2023). "Thus, TLR4 inhibitors or CD38 activators may serve as potential drugs to attenuate E. coli-induced liver injury in septicemia." (PMID 33860064, 2021). "In sepsis-related brain damage in rats, however, the CD38/cADPR pathway may promote apoptosis." (PMID 32093678, 2020). "Therefore, the role of CD38 in the immunosuppressive phase of sepsis should also be investigated." (PMID 31963337, 2020). "Meanwhile, we found that CD38 gene deficiency could aggravate AKI in LPS-induced sepsis, which is not consistent with the reports above." (PMID 30915370, 2019).
Sepsis (continued). "Our findings indicate that an MFI of CD38 ≥ 14 382 in CD14+ monocytes can serve as a threshold to define CD38high monocytes, effectively differentiating sepsis from non‐infectious inflammation." (PMID 40145840, 2025). "Glycolytic metabolite methylglyoxal (MGO) is found to regulate expression of CD38, establishing a CD38‐HIF‐1α/glycolysis/MGO loop that exacerbates sepsis‐induced immune dysregulation." (PMID 40145840, 2025). "To confirm this, we used an NAMPT inhibitor, FK866, in this sepsis model and observed that FK866 significantly attenuated kidney injury and IL-6 production induced by LPS and CD38 ligation." (PMID 39568061, 2025). "The percentage of CD38+CD8+T cells, PD-1+NK cells, HLA-DR+ CD8+T cells represented the top three highest SHAP value contributions in the segregation of patients with sepsis from HCs in the XGBoost model." (PMID 38953031, 2024). "According to the latest research, LPS or polymicrobial sepsis-induced mortality in CD38−/− mice were markedly augmented compared with wild types, and CD38−/− macrophages displayed markedly increased activation of NF-κB and NLRP3." (PMID 36998049, 2023). "In CLP sepsis, there was a two-fold increase in the frequency of the TLR4-positive CD34+ CD38− cells (55 ± 13.4 % versus 26.1 ± 13.4 %)." (PMID 26272069, 2015). "Collectively, these results provided evidence of our hypothesis that the CD38‐NAD+‐HIF1‐α/glycolysis/MGO loop promoted the activation of monocytes and therefore exacerbated sepsis‐induced immune dysfunction." (PMID 40145840, 2025). "In addition, our study has revealed a CD38‐NAD+‐HIF‐1α/glycolysis/MGO positive feedback loop that exacerbates monocytes activation and dysfunction in sepsis." (PMID 40145840, 2025). "Although several in vitro studies have reported that CD38 ligation induces cytokine production and cell adhesion in macrophages and monocytes, studies investigating the effects of CD38 ligation in in vivo sepsis models are lacking." (PMID 39568061, 2025). "Interestingly, in our models, the expression of TLR4 was upregulated on both CD34+ CD38− and CD34+ CD38+ cells and this is in contrast to modulation of those receptors on monocytes from patients with sepsis." (PMID 26272069, 2015). "CLP-induced sepsis increased both the frequency (3.8 ± 1.1 % versus 0.65 ± 0.32 %, P < 0.01) and total cell count (1.5 × 105 ± 0.8 × 105/ml versus 0.3 × 105 ± 0.2 × 105/ml, P < 0.05) of the early CD34+ CD38− HSPCs." (PMID 26272069, 2015). "The reason for the discrepancy may be that the gene ratio CD16/CD38 is not as specific for sepsis as the cell ratio." (PMID 38053180, 2023). "Therefore, we investigated in CD38−/− mice whether IFN-γ is still a dangerous factor that promotes sepsis progression induced by LPS challenge, with the aim of indicating a potential therapeutic field to overcome sepsis." (PMID 30915370, 2019). "Key markers of immune dysfunction in sepsis, such as HLA-DR expression on monocytes, T cell activation/exhaustion markers (e.g., CD28, CD38), were not assessed." (PMID 41346598, 2025).
prostate carcinoma (26 papers, 2009 to 2025). A carcinoma that arises from epithelial cells of the prostate gland. "The findings of further studies have indicated that the progression of prostate cancer is associated with increases in CD38+ tumor-infiltrating immune cell density, which is independently associated with a worse OS." (PMID 38404585, 2024). "Collectively, these findings provide additional insight supporting the functional relevance of CD38 loss in prostate cancer by linking cell-autonomous regulation of mitochondrial function and prostate cancer." (PMID 35677882, 2022). "In this setting, CD38 expression is associated with prostate cancer progression, presumably due to its extracellular enzymatic activity leading to the synthesis of immunosuppressive adenosine." (PMID 35677882, 2022). "Recently, PIA-like, low CD38-expressing, inflammation-associated luminal cells were shown to initiate prostate cancer." (PMID 35328625, 2022). "We identified loss of expression of CD38 protein as a prognostic biomarker that correlates with several features of aggressive prostate cancer including advanced stage (T3 including both SVI and ECE) and RFS." (PMID 29464091, 2018). "CD38 expression, its association with recurrence after prostatectomy for clinically localized prostate cancer, and DNA methylation of the CD38 promoter were evaluated in human prostate tissues representing various stages of disease progression." (PMID 30258629, 2018). "Specifically, we have identified CD38 as a marker of differentiation in prostate cancer and confirmed that decreased of expression of CD38 transcripts and protein by IHC is associated with aggressive prostate cancer." (PMID 29464091, 2018). "Heterogeneous loss of CD38 in prostate cancer samples compared to normal prostate tissues has been observed in a broad survey of cell surface (CD) marker expression." (PMID 29464091, 2018). "Reduced expression of CD38 is common in prostate cancer and associated with recurrence after prostatectomy for clinically localized disease, but the mechanisms repressing CD38 expression are poorly understood." (PMID 30258629, 2018). "Since CD38 expression results in deficient fatty acid and lipid synthesis, this may be detrimental to the adipogenic phenotype of prostate cancer." (PMID 40382743, 2025). "Loss of CD38 confers a metabolic advantage during carcinogenic transformation of prostate cancer." (PMID 34490029, 2021). "CD38 has been linked to the inhibition of the metabolism and the proliferation in prostate cancer." (PMID 33763366, 2021). "In a limited cohort, a few studies have reported loss of CD38 expression in prostate cancer." (PMID 30258629, 2018). "CD38 protein expression in prostate cancer is associated with risk of recurrence." (PMID 30258629, 2018). "Outside of a functional role in prostate tumorigenesis, we and others have established CD38 as a marker of differentiated prostate luminal cells, suggesting that loss of CD38 in prostate cancer may primarily serve as a marker of a de-differentiated or progenitor-like state." (PMID 30258629, 2018). "In contrast, another study demonstrated that CD38 expression is negatively correlated with tumor progression in prostate cancer." (PMID 40382743, 2025). "Immunohistochemical results from the Human Protein Atlas (HPA) database suggested decreased protein expression levels of CD38 in prostate cancer tissues, while MMP11 and PLK1 showed moderate expression in both normal and cancerous tissues." (PMID 41415207, 2025). "Although MMP11 remains our primary focus based on previous studies, the critical role of CD38 in prostate cancer development warrants concurrent investigation." (PMID 41001131, 2025). "For example, in pancreatic cancer and prostate cancer, low CD38 expression increases tumor cell survival." (PMID 38545257, 2024). "CD38 is highly expressed in lung and cervical cancer in contrast with its low expression in prostate cancer." (PMID 38545257, 2024).
prostate carcinoma (continued). "CD38 expression however remain detectable in bulk prostate cancer tissues mainly due to its expression in cell types other than the prostate cancer cells." (PMID 35677882, 2022). "Among the three categories of NAD+-dependent enzymes, CD38 is of particular relevance to prostate cancer because its expression is downregulated in prostate cancer." (PMID 35677882, 2022). "This notion is consistent with our finding that NAD+ depletion by CD38, in turn, was fatal to prostate cancer cells." (PMID 35677882, 2022). "In one of our earlier expression microarray data set comparing prostate cancer tissues with paired adjacent normal prostate tissues, CD38 was among one of the most consistently downregulated genes in prostate cancer." (PMID 35677882, 2022). "Findings from recent studies provided important insights in relation to the role of CD38 in prostate cancer." (PMID 35677882, 2022). "An emerging biomarker in prostate cancer, expressed in both tumor and immune cells, is the ectoenzyme CD38." (PMID 34638258, 2021). "CD38 demonstrated a significant (p<0.05) decrease in stage 2 and 3 prostate cancers compared with BPH." (PMID 34019593, 2021). "A recent work has highlighted an increase in CD38+ tumor-infiltrating immune cells in prostate cancer specimens after the onset of castration resistance, a high level being correlated to worse OS." (PMID 34638258, 2021). "Another study confirmed that CD38 expression is inversely correlated with tumor progression in prostate cancer, and this corresponds with increased NAD+ levels in the tumor." (PMID 31878283, 2019). "For example, pancreatic and prostate cancer, which exhibit low CD38 expression and increased cellular NAD+ levels, exhibit increased tumor cell survival." (PMID 31214171, 2019). "The overexpression of CD38 in prostate cancer cells decreased proliferation with an increase in cell doubling time, as well as decreased glycolytic and metabolic capacity." (PMID 31878283, 2019). "Results were replicated using LNCaP and DU145 prostate cancer cells expressing wild-type or mutant CD38." (PMID 30258629, 2018). "Methylation results suggest that CD38 is epigenetically regulated in localized and metastatic prostate cancer tissues." (PMID 30258629, 2018). "We recently reported that human prostate cancer can be initiated following oncogene expression in progenitor-like luminal cells marked by low expression of the NAD+-consuming enzyme CD38." (PMID 30258629, 2018). "RNA sequencing data indicates a clear trend with CD38 mRNA expression lower in primary prostate cancer than in benign prostate, and further reduced in CRPC tissues." (PMID 30258629, 2018). "CD38 mRNA expression was reduced in metastatic castration-resistant prostate cancer compared to localized prostate cancer." (PMID 30258629, 2018). "We previously demonstrated that CD38 mRNA and protein expression is reduced in primary prostate cancer, but the expression of CD38 in metastatic prostate cancer is poorly defined." (PMID 30258629, 2018). "We therefore propose a model whereby repression of CD38 due to methylation enhances the extracellular pool of NAD+ in prostate cancer." (PMID 30258629, 2018). "Several key questions remain unanswered, including What is the level of CD38 expression in metastatic castration-resistant prostate cancer?" (PMID 30258629, 2018). "We identified two genes, CD38 and ARG2 that appear to be associated with prostate cancer differentiation." (PMID 29464091, 2018). "To further evaluate CD38 expression in advanced disease, we interrogated transcriptional profiles of patient tissues representing benign prostate, primary prostate cancer, and castration-resistant prostate cancer (CRPC)." (PMID 30258629, 2018).